AP2M1 (adaptor related protein complex 2 subunit mu 1)
Diseases named in the same sentence as AP2M1 in open-access papers (continued):
Sharing a sentence is not in itself a finding about the gene and the disease.
infection (14 papers, 2011 to 2026). The state of being infected such as from the introduction of a foreign agent such as serum, vaccine, antigenic substance or organism. "This is likely the case in the liver, where both ap2m1 and dynamin-2 in ITGB1b-deficient rare minnows were lower than that of the wild-type minnows early during infection." (PMID 30326628, 2018). "We also perform the shRNA knockdown of the μ-subunit of the adaptor protein AP-2 (AP2M1), which plays an important role in the maturation of clathrin-coated vesicles, and the infection is greatly reduced when this subunit is knocked down." (PMID 38374920, 2024). "While virus production also remained modest after infection of AP2M1 clone 39 cells, a clear rise in extracellular p24 levels nevertheless became evident after an initial lag period." (PMID 36622146, 2023). "Specific siRNA silencing tests showed that ERA-mCherry infection was inhibited by AP2M1 knock-down in HEK293 cells and SK cells." (PMID 31905947, 2019). "The phosphorylation of AP2M1 was significantly enhanced upon ERA-mCherry infection, and the phosphorylation was effectively inhibited by sunitinib but not erlotinib." (PMID 31905947, 2019). "The results showed that the growth of ERA-mCherry in AP2M1 (T156A)-transfected HEK293 cells was significantly reduced compared with that in AP2M1- and pCAGGS-transfected cells at different time points post-infection." (PMID 31905947, 2019). "Notably, inhibition of the NAKs-AP2M1 axis effectively reduced infection across multiple PRRSV strains, highlighting its capacity as a broad-spectrum antiviral target." (PMID 41982333, 2026). "Once the AP2M1 KOs were validated, the infection of C5 and C7 with HCoV-229E-GFP was performed." (PMID 39456165, 2024). "In addition, the low infection rates when infecting AP2M1 KO cells provide further evidence." (PMID 39456165, 2024). "AAK1 knock-down greatly inhibits RABV infection of cells, and AAK1-induced phosphorylation of threonine 156 of the μ subunit of adaptor protein 2 (AP2M1) is found to be required for RABV entry." (PMID 31905947, 2019). "In contrast, infection with J6/JFH virus appeared to significantly increase the localization of AP2M1 to LD, with 40±8% of LD being AP2M1 positive (p-value = 0.0006)." (PMID 22916011, 2012). "Disruption of AP2M1 phosphorylation or blockade of the AP2M1-YxxØ interaction significantly impaired PRRSV internalization, indicating the potential for targeting this pathway to inhibit infection." (PMID 41982333, 2026). "Compared to the wild-type non-KO cells, the infection of cells that did not express AP2M1 was reduced significantly, more than 50%, as seen in the flow cytometry data, viral titration and immunoblot." (PMID 39456165, 2024). "Depletion of AP2M1 resulted in decreased viral infectivity after infection but not after transfection with viral RNA which confirms the involvement of CME in the entry process of CHIKV." (PMID 33717005, 2021). "Our crosslinking experiment validates the complex’s structural assembly on the membrane as AP2M1 was selectively crosslinked at 0 min of infection, while no other AP-2 subunits were observed." (PMID 32753727, 2020). "The results showed that although the level of jam-a and caveolin-1 expression did not change significantly during the infection, the expression of ap2m1 and dynamin-2 in the various tissues exhibited significant changes." (PMID 30326628, 2018). "To examine the roles of clathrin-dependent endocytic pathway in the enhancement of EV71-infection by CPZ, we performed siRNA knockdown of the AP2M1, CLTC, DNM2 and FCHO2 (the reported crucial CME components) in A549 and RD cells and tested the viral infectivity with additional CPZ treatment." (PMID 29298696, 2018). "Notably, extracellular p24 levels after infection with Nef-deficient HIV-1NL4-3 were comparable in the presence and absence of ectopically expressed AP2M1." (PMID 36622146, 2023).
infection (continued). "Unexpectedly, although baricitinib has been shown to own high affinity to AAK1, it did not display obvious inhibition on the phosphorylation of AP2M1 unless at very high dose (10 μM), and consequently displayed no inhibitory effect on infection of each type of pseudovirus." (PMID 33083006, 2020). "Overexpression of wild-type AP2M1, but not the phosphorylation mutant, significantly increased TOSV infection by ∼30%, suggesting that AP2 is rate-limiting for infection." (PMID 39017647, 2024). "Some factors identified in our screen might have been predicted: AP2M1 and DNM2, two components of the endocytic pathway were identified in the primary screen to restrict infection of cells by the pseudovirus but not by wild type HIV-1 viruses." (PMID 22082156, 2011).
cancer (10 papers, 2019 to 2025). A tumor composed of atypical neoplastic, often pleomorphic cells that invade other tissues. "We confirmed these cancer‐favorable properties are closely associated with the Notch1 signaling pathway, which is most prominently activated in malignant AP2M1+ HSPCs of human samples." (PMID 41082341, 2025). "Recently, AP2M1 has been found to be associated with several types of cancer." (PMID 32943990, 2020). "Given the limited understanding of AP2M1, our research aims to elucidate its role by examining its function in normal hematopoiesis and extending its impact on cancer development and drug treatment responses." (PMID 41082341, 2025). "AP2M1 expression distinctly differentiates normal from malignant cells, surpassing well‐recognized cancer stem cell markers, ATP‐binding cassette transporters, known for drug efflux and chemoresistance." (PMID 41082341, 2025). "We observed that in the control group, four out of nine organisms had remaining cancer cells after anticancer drug treatment, whereas in the ap2m1 overexpression group, eight out of nine organisms showed residual cancer cells following treatment." (PMID 41082341, 2025). "To investigate the role of AP2M1 expression in drug resistance in cancer cells, we treated cells with idarubicin and assessed cell viability, proliferation, and sub‐G1 arrest." (PMID 41082341, 2025). "We examined the expression of ATP‐binding cassette (ABC) transporters, which, like AP2M1, are responsible for intracellular substance transport and are widely recognized as cancer stem cell markers." (PMID 41082341, 2025). "Our findings, which are consistent with previous research, indicated that RAB32, SMYD3, AP2M1, and HSP90B1 were associated with cancer progression." (PMID 35610596, 2022). "Previous findings suggested that AP2M1 has a close relationship with various types of cancers." (PMID 41082341, 2025). "Additionally, it was shown that AP2M1 protein contributed to the anti-tumor effects of ALT on cancer cells by modulating autophagy." (PMID 32943990, 2020). "Importantly, our findings revealed that AP2M1 exerts a significant influence on the expression levels of NOTCH1, a key regulatory gene in hematopoiesis and cancer development." (PMID 41082341, 2025). "As observed in the case of tongue, genes associated with overall cohort, IL1RAP, ANO1, RYK, AP2M1, MFN1 and PSMD2 were significant prognosticators only in the late stage not in early cancers." (PMID 31310629, 2019). "All these genes (AP2M1, FKBP11, GALNT6, BDNF, COL9A3 and NR4A1) favor relevant features of cancer progression, indicating that their epigenetic activation in CTCs of CRC patients under treatment could be a key event for the development of therapy resistance and cancer progression." (PMID 38188020, 2023).
tumor (7 papers, 2020 to 2025). "Given that self‐renewing and multipotent tumor cells inherently resist anticancer therapies, the observed chemoresistance induced by AP2M1 prompted an investigation into its impact on the stemness in AML patients." (PMID 41082341, 2025). "Inducing shAP2M1 in BXPC-3 cells reduced AP2M1 protein and significantly increased tumor spheroid size compared to shCTRL in three independent experiments." (PMID 40050266, 2025). "The present study demonstrated that ALT exerts anti-tumor activity through inducing apoptosis and inhibiting autophagy by upregulating AP2M1 in ALL, highlighting a potential therapeutic strategy for treatment of ALL." (PMID 32943990, 2020). "CD34 is the classical maker gene for tumor vessels; in addition, Cltc, Canx, and Ap2m1 were highly expressed in tumor vessels; these vessels could transport nanoparticles into tumor stroma." (PMID 36382024, 2022). "Additionally, it was demonstrated that ALT inhibited cell proliferation, colony formation, autophagy, induced apoptosis and reduced tumor growth in vivo through upregulating the expression of adaptor related protein complex 2 subunit mu 1 (AP2M1)." (PMID 32943990, 2020). "Accordingly, these results indicate ALT suppresses tumor growth in vivo, and this effect could be reversed by knockdown of AP2M1." (PMID 32943990, 2020). "Taken together, the results of the present study suggest that ALT may maintain cellular homeostasis between autophagy and apoptosis by increasing AP2M1, and thereby exerting anti-tumor activity in ALL." (PMID 32943990, 2020). "Importantly, AP2M1 was shown to mediate the anti-tumor effects of ALT on BV173 and NALM6 cells." (PMID 32943990, 2020). "From day 14, tumor volume in the ALT group was significantly lower compared with the control group, whereas xenograft tumor volume in the co-treatment group with ALT and si-AP2M1 was larger compared with the ALT treated group (alone) (P < 0.05)." (PMID 32943990, 2020). "Interestingly, CFPAC-1 endocytosis of ITGB1 was not affected by AP2M1 depletion or Pitstop2 treatment, validating the results of the plasma membrane proteomics and suggesting that integrin endocytosis is independent of clathrin in cell lines where AP2 loss did not enhance tumor growth." (PMID 40050266, 2025).
neurodegenerative disease (1 paper, 2022). A disorder of the central nervous system characterized by gradual and progressive loss of neural tissue and neurologic function. "A growing number of studies have demonstrated the potential impact of AP2M1 on neurodegenerative disease." (PMID 36468008, 2022).
AP2M1 also shares sentences with these, for which no sentence is quoted: acute lymphoblastic leukemia (2 papers); neurodevelopmental disorder (2); acute myeloid leukemia (1); adenoid cystic carcinoma (1); chronic myeloid leukemia (1); Cognitive impairment (1); colorectal cancer (1); COVID-19 (1); Epstein-Barr virus infection (1); esophageal squamous cell carcinoma (1); Fibroadenoma (1); frontotemporal dementia (1); Global developmental delay (1); head and neck squamous cell carcinoma (1); hepatitis C (1); Huntington disease (1); Intellectual disability (1); intervertebral disc degeneration (1); liver steatosis (1); lymphoma (1); medulloblastoma (1); metabolic disease (1); migraine (1); oral cancer (1); ovarian carcinoma (1); Parkinson disease (1); schizophrenia (1).